TLR4 (toll like receptor 4)
Diseases named in the same sentence as TLR4 in open-access papers (continued):
Sharing a sentence is not in itself a finding about the gene and the disease.
cervical carcinoma (continued). "Our present results show that IgG is recruited to TLR4 and elevates its expression to boost TLR4 signaling which was reported to enhance cervical cancer cell proliferation and anti-apoptosis." (PMID 25179302, 2014). "The results showed that TLR4 mean density of cervical cancer tissues was higher than that of normal cervical tissues." (PMID 25179302, 2014). "To further test the effects of IgG on TLR4 expression, we observed TLR4 dynamics after LPS treatments of cervical cancer cells." (PMID 25179302, 2014). "TLR4 signaling plays a positive role in the development of many inflammation induced cancers such as cervical cancer." (PMID 25179302, 2014). "TLR-4 was overexpressed in cervix cancer, and its activation by LPS promotes proliferation and anti-apoptosis in HeLa cells in vitro." (PMID 25297386, 2014). "Further mechanistic studies revealed that berberine, the primary active component of berberine hydrochloride, significantly inhibits the proliferation and migration of cervical cancer HeLa cells by downregulating Bcl-2 expression through the TLR4/NF-κB signaling pathway, thereby promoting apoptosis." (PMID 40260114, 2025). "TLR4 expression has been correlated with tumor grade in HPV-related cervical carcinoma." (PMID 39451550, 2024). "In this way, the chronic inflammatory status of the cervix, caused by its susceptibility to microbial infection and as a result of sexual activity, together with TLR4, represent key endogenous factors able to promote an immunosuppressive microenvironment and cervical carcinoma progression." (PMID 39451550, 2024). "Furthermore, pro-inflammatory cytokines, such as COX-2, iNOS, IL-6, IL-8, MIP-3α, TGF-β1, and VEGF, are upregulated in HPV-related cervical cancer cells in vivo following the activation of the TLR4/MyD88/NF-KB pathway." (PMID 39451550, 2024). "Previous studies performed on cervical carcinoma cell lines demonstrated a higher TLR4 expression in the HPV-positive cervical cancer cell lines SiHa and HeLa, compared with the HPV-negative cell line C33A, indicating a role for HPV infection in TLR4 regulation." (PMID 39451550, 2024). "Moreover, higher TLR4 expression in HPV-positive cervical cancer cell lines SiHa and HeLa, compared with the HPV-negative cell line C33A, was observed, indicating a role for HPV infection in TLR4 regulation." (PMID 37370894, 2023). "Next, we sought to discover whether ICA inhibits cervical cancer progression through TLR4/MyD88/NF-κB and Wnt/β-catenin signaling pathways in vivo and in vitro." (PMID 33849528, 2021). "TLR4 promoted the growth of cervical tumors and facilitated the formation of a local immune microenvironment both in vitro and in vivo and eventually promoted the development and progression of cervical cancer." (PMID 32095158, 2020). "However, the relationship between TLR4 and cervical cancer development remains controversial, and the carcinogenic mechanism has not been fully elucidated." (PMID 32095158, 2020). "In addition, this study increases our understanding of the pathogenesis of HPV-related cervical cancer and provides clues to enable the exploration of new therapeutic methods to treat cervical cancer by targeting TLR4-relevant molecules." (PMID 32095158, 2020). "In conclusion, this study further confirms the hypothesis that TLR4 plays an important tumor-promoting role in HPV-related cervical cancer, which depends mainly on the formation of an immunosuppressive microenvironment." (PMID 32095158, 2020). "In our previous study, we found that TLR4 promotes cervical cancer cell growth in vitro." (PMID 32095158, 2020). "Since these haplotypes included both risk as well as protective alleles, a crucial role of TLR4 and TLR9 polymorphisms may be envisaged towards HPV infection and cervical cancer susceptibility." (PMID 31278284, 2019).
cervical carcinoma (continued). "POL-P3b could inhibit the growth of cervical carcinoma by oral administration and the mechanism was related to inducing protection against tumor-induced intestinal DC apoptosis through stimulating the TLR4/PI3K/AKT-NF-κB signaling pathway." (PMID 31277622, 2019). "Interestingly, previous studies have shown that TLR2 G753A SNPs are associated with urinary tract infection, TLR4 C399T SNPs are associated with various infections and Crohn's disease, and TLR9 G2848A SNPs are associated with cervical cancer." (PMID 30116270, 2018). "Similarly, the use of LPS-derivative MPL for TLR4 stimulation and TLR7 agonist imiquimod has been restricted to vaccine formulations against HPV-associated cervical cancers and to topical treatments for basal-cell skin carcinomas, respectively." (PMID 26177198, 2015). "We examined TLR4 expression in cervical cancer cells after IGHG1 silencing." (PMID 25179302, 2014). "Our study strongly indicates that IgG may promote cervical cancer cell proliferation through enhancing TLR4 signaling." (PMID 25179302, 2014). "In other words, the physiological significance of IgG in cancer immunology is that it may contribute to the development of cervical cancer through positively regulating TLR4 signaling pathways." (PMID 25179302, 2014). "In the meantime, IgG knockdown also downregulated TLR4 expression in cervical cancer cells." (PMID 25179302, 2014). "Similarly, other authors have demonstrated high TLR4 expression in cervical carcinoma." (PMID 39451550, 2024). "Thus, although TLR4 is considered an important marker of HPV+ cervical cancer, alterations in the levels of TLR1, TLR3 and TLR6 observed in HPV+ samples may be the target of investigations related to the tumor inflammatory process." (PMID 39208235, 2024). "However, whether TLR4 can promote the HPV-related cervical cancer inflammatory microenvironment in vivo remains to be explored." (PMID 32095158, 2020). "Moreover, proinflammatory cytokines are highly expressed in HPV-related cervical cancer cells when the TLR4/MyD88/NF-κB pathway is activated, which indicates that TLR4 promotes cervical cancer progression via the formation of an immunosuppressive microenvironment." (PMID 32095158, 2020). "Furthermore, Portulaca oleracea L. Polysaccharide (POL-P3b) could inhibit the expression of TLR4, MyD88, TRAF6, AP-1, and NF-κB subunit P65 in HeLa cells, thereby inhibiting the TLR4/NF-κB pathway to induce Cervical cancer cells apoptosis." (PMID 32536869, 2020). "However, expression analysis of TLR4 and TLR9 genes may provide more insights into the functional role of these UTR SNPs in cervical cancer risk." (PMID 31278284, 2019). "Furthermore, within cases, haplotypes analysis did not reveal an association of either TLR4 (Pglobal = 0.733) or TLR9 (Pglobal = 0.546) haplotypes with the early or late stages of cervical cancer." (PMID 31278284, 2019). "We found that the expressions of key genes and proteins in the TLR4/NO signaling pathway were upregulated in HR-HPV-positive cervical cancer tissues and cells, suggesting that TLR4/NO signaling pathway activation may participate in the pathogenesis of cervical cancer caused by HR-HPV infection." (PMID 28626766, 2017). "Based on our results, we speculate that TLR4 pathway activation is associated with HR-HPV infection and may participate in the regulation of the local cervical immune microenvironment and the pathogenesis of cervical cancer." (PMID 28626766, 2017). "When evaluating the gene expression patterns of TLR transcripts, specifically TLR1, TLR3, TLR4, TLR6, TLR7, TLR8 and TLR10, in HPV+ and HPV- cervical cancer tissue samples, we observed an increase in TLR4 expression and a decrease in TLR1 and TLR3 expression." (PMID 39208235, 2024). "Specifically, a close relation between TLR4 expression and FIGO stage, lymph node metastases, and tumor size has been reported in cervical cancer." (PMID 39451550, 2024).
cervical carcinoma (continued). "Increasing scientific evidence suggests that TLR4 promotes tumor growth and facilitates the formation of a local immunosuppressive microenvironment in HPV-positive cervical carcinoma." (PMID 39451550, 2024). "Growing scientific evidence suggests a link between the expression of toll-like receptor 4 (TLR4) and cervical cancer carcinogenesis." (PMID 39451550, 2024). "Other TLR4 activators like AS04 (MPL derivative, cervical cancer) and GLA-SE (lymphoma Merkel cell carcinoma) are also studied via preclinical and clinical studies." (PMID 37936697, 2023). "Here, we studied the receptor TLR4 and the adaptor molecule SARM1 in HeLa cells, an HPV-positive cervical cancer cell line." (PMID 35468924, 2022). "To study the role of TLR4 and SARM1 in the malignant phenotype of cervical cancer cells, we knocked out these genes individually in HeLa cells using CRISPR/Cas9 and isolated individual clones of the edited cells." (PMID 35468924, 2022). "Here we show that the expression of IL6 and IL18 is modulated by TLR4 and SARM1 in cervical cancer cells." (PMID 35468924, 2022). "To determine if TLR4 and SARM1 impact the response of cervical cancer cells to chemotherapy, we treated parental, TLR4KO and SARM1KO cells with different concentrations of cisplatin." (PMID 35468924, 2022). "Multiple TLR4 activators have been studied in experimental and clinical trials, including AS04 (FDA-approved for cervical cancer), MPLA (derivative of lipid A, cervical cancer), and GLA-SE (G100-synthetic GLA, lymphoma tumor)." (PMID 34124272, 2021). "In our previous study, we explored the relationship between TLR4 and cervical cancer cells in vitro and found that TLR4 promoted proliferation and apoptosis resistance in HPV-related cervical cancer cells." (PMID 32095158, 2020). "Thus, IgG might promote cervical cancer proliferation by enhancing TLR4 signaling." (PMID 28854209, 2017). "Despite this, the role and mechanism of the TLR4/NO signaling pathway in other types of HPV infection, as well as the role of other receptor pathways in HPV infection and cervical cancer, require further investigation." (PMID 28626766, 2017). "In our study, the expression levels of TLR3, TLR4, TLR7, TLR8, NF-κB p65, and iNOS mRNA in the cervical squamous epithelial cells were significantly higher in the cervical cancer group than in the HR-HPV patients and healthy controls." (PMID 28626766, 2017). "Studies also found that TLRs, especially TLR4, TLR5 and TLR9, are closely related to HPV infection and cervical cancer." (PMID 29263932, 2017). "Specific mechanisms of the TLR4/NO pathway and HR-HPV involved in cervical cancer need further exploration." (PMID 29263932, 2017). "A link between increased TLR4 expression and the severity of cervical lesions was also documented, such as a close relationship between TLR4 expression and FIGO stage, lymph node metastases, and tumor size has been reported in cervical cancer." (PMID 39451550, 2024). "Additionally, compared to the HPV-negative cell line C33A, there was greater TLR4 expression in the HPV-positive cervical cancer cell lines SiHa and HeLa, suggesting a role for HPV infection in TLR4 regulation." (PMID 39451550, 2024). "In conclusion, TLR4 and SARM1 are important for therapy resistance and cervical cancer cell viability and may be relevant clinical targets." (PMID 35468924, 2022). "Furthermore, we found that TLR4 promoted the expression of proinflammatory cytokines such as COX-2, iNOS, IL-6, IL-8, MIP-3α, TGF-β1 and VEGF in HPV-related cervical cancer cells in vivo." (PMID 32095158, 2020). "Moreover, in our previous study, we found that TLR4 was highly expressed in cervical cancer and that TLR4 promoted proliferation and resistance to apoptosis in HPV-related cervical cancer cells." (PMID 32095158, 2020).
cervical carcinoma (continued). "To identify the strong coinheritance of the SNPs we calculated linkage disequilibrium of TLR4 and TLR9 SNPs, wherein TLR4 rs10759931 and rs1927911, and TLR9 rs187084 and rs352139 were in strong LD, evincing strong influence of these inherited variations in cervical cancer." (PMID 31278284, 2019). "Previous studies demonstrated that cervical cancer tissues expressed TLR4 and proinflammatory cytokines at high level, compared to normal cervical tissues." (PMID 25179302, 2014). "We tested the TLR3, TLR4, TLR7, TLR8, NF-κB p65, and iNOS mRNA expression levels in the cervical tissue epithelial cells of the three groups and found that all mRNA levels were higher in the cervical cancer group than in the HR-HPV group and control group (P < 0.05)." (PMID 28626766, 2017). "Western blot results showed that IgG did not affect the protein levels of MyD88, IRAK1, and TRAF6 (data not shown), indicating that TLR4 was at least the major target involved in IgG-mediated positive regulation of LPS-induced proinflammatory cytokine production in cervical cancer cells." (PMID 25179302, 2014). "Since the high expression of TLR4 is closely linked with the development of cervical cancer but is not mediated by HPV, we reasoned that other pathogens, such as bacteria, may activate the TLR4 pathway to facilitate immune escape, which promotes the development of cervical lesions." (PMID 29263932, 2017).
acute lung injury (56 papers, 2009 to 2026). A condition of lung damage that is characterized by bilateral pulmonary infiltrates (pulmonary edema) rich in neutrophils, and in the absence of clinical heart failure. "Previous studies have indicated that sodium butyrate (NaB) inhibits the inflammation of lipopolysaccharide (LPS)-induced acute lung injury (ALI) by regulating the toll-like receptors 4 (TLR4)/nuclear factor kappa-B (NF-κB) signaling pathway." (PMID 37754570, 2023). "TLR4 signaling pathway has been found to be closely related to the occurrence and development of acute lung injury (ALI)." (PMID 35874106, 2022). "Similar to our findings, a study focused on the effect of paeonol on acute lung injury (ALI) has demonstrated that paeonol ameliorates LPS-induced ALI via inhibition of the TLR4/MyD88/NF-κB signalling pathway." (PMID 35303801, 2022). "This review focuses on the role of TLR4 in the development of virus-induced acute lung injury (ALI) and its potential for therapeutic targeting." (PMID 34282358, 2021). "Hesperetin has been shown a potential drug for acute lung injury (ALI) induced in vivo by lipopolysaccharide by downregulated the Toll-like receptor 4 (TLR4) and suppressed NF-κB activation in lung tissue." (PMID 33057955, 2020). "Numerous studies have suggested that a signalling pathway mediated by Toll-like receptor 4 (TLR4) plays a pivotal role in the pathogenesis of this inflammatory response in acute lung injury (ALI)." (PMID 33062073, 2020). "DAMPs mediated TLR4 signaling also plays a central role in acute lung injury (ALI)." (PMID 40356926, 2025). "Therefore, SARS-CoV-2-induced acute lung injury (ALI)/ARDS is caused by the downregulation of ACE2, activation of the NLRP3 inflammasome and TLR2/TLR4, and autophagy." (PMID 36851766, 2023). "Our results are in agreement with other reports that baicalin, a bioactive component of QHSG, inhibits the secretion of inflammatory factors in LPS-induced acute lung injury in rats by suppressing the TLR4/myeloid differentiation factor 88 (MyD88)/NF-κB signaling pathway." (PMID 37954597, 2023). "For example, MiR-16 could suppress NLRP3 inflammasome activation by targeting Toll-like receptor 4 directly in acute lung injury (ALI)." (PMID 36523634, 2022). "In human acute lung injury (ALI), the activation of RHOB potentiates the TLR4/NF-κB signaling pathway activity, resulting in the release of inflammatory factors." (PMID 36231106, 2022). "Previously, we reported that a signaling cascade involving HMGB1, toll-like receptor 4 (TLR4), interleukin 23 (IL23), and IL17A mediated acute lung injury (ALI) in a mouse model of paraquat poisoning." (PMID 31092889, 2019). "A membrane component of Gram-negative bacteria lipopolysaccharide (LPS), which is used in experimental acute lung injury (ALI) models, and interacts with toll-like receptor 4 (TLR4), which initiates an inflammatory, and immune response." (PMID 29853535, 2018). "In a rat model of acute lung injury (ALI) with pulmonary hemorrhage and inflammation, BPs ameliorated lung injuries and suppressed TLR4 expression." (PMID 24167596, 2013). "During acute lung injury (ALI), HMGB1 facilitates the polarization of macrophages toward the M1 phenotype and exacerbates ALI via the NF-κB signaling pathway mediated by TLR2 and TLR4." (PMID 41041277, 2025). "It has been well-documented that ketamine can ameliorate acute lung injury (ALI) induced by high mobility group box-1 protein (HMGB1), which might be realized via the toll-like receptor 4 (TLR4) signaling pathway." (PMID 40033510, 2025). "In the lungs, LPS recognition by Toll-like receptor 4 (TLR4) on bronchial epithelial cells and lung macrophages contributes to acute lung injury (ALI) and triggers innate immune responses, the release of inflammatory mediators, and activation of the NF-κB pathway." (PMID 37760027, 2023).
acute lung injury (continued). "In conclusion, PIC may be potential to treat LPS-induced acute lung injury (ALI) via regulating air-blood barrier and TLR4/NF-κB signaling pathway activation." (PMID 32038265, 2019).